PGK1 (phosphoglycerate kinase 1)
Diseases named in the same sentence as PGK1 in open-access papers (continued):
Sharing a sentence is not in itself a finding about the gene and the disease.
lung adenocarcinoma (4 papers, 2019 to 2022). A carcinoma that arises from the lung and is characterized by the presence of malignant glandular epithelial cells. "In this study, we evaluate the associations of PGK1 with prognosis and immunological characteristics in lung adenocarcinoma using bioinformatic analysis methods." (PMID 36358653, 2022). "We further statistically analyzed the PGK1 protein expression in relation to migration ability, and the results showed that they were positively correlated in various lung adenocarcinoma cells (Pearson ρ = 0.683, p = 0.043)." (PMID 34091600, 2021). "We collected and established a lung adenocarcinoma cell panel for screening the endogenous PGK1 protein levels." (PMID 34091600, 2021). "We conclude that even though PGK1 promoted lung adenocarcinoma migration, it relied on the interaction of PGK1 protein–protein binding with HTATSF1 rather on metabolic events." (PMID 34091600, 2021). "The enrichment analysis of PGK1 co-expressed genes in lung adenocarcinoma revealed that PGK1 may be involved in hypoxia, metabolism, DNA synthesis, cell cycle, PI3K/AKT, and various immune and inflammatory signaling pathways." (PMID 36358653, 2022). "Therefore, we further investigated the role of PGK1 in lung adenocarcinoma." (PMID 34091600, 2021). "At the same time, we also performed a single cell sequencing analysis of the tumor immune microenvironment in lung adenocarcinoma in GSE131907 in a scTIME Portal and evaluated the expression of PGK1 in tumor cells and immune cells." (PMID 36358653, 2022). "The results indicated that the expression of PGK1 was distinctly upregulated in most types of cancers, including bladder urothelial carcinoma (BLCA), head and neck squamous cell carcinoma (HNSCC), and lung adenocarcinoma (LUAD)." (PMID 34668665, 2021). "In this study, we found that PGK1 has a negative effect on the survival of lung adenocarcinoma patients, which might be due to PGK1’s mediating interaction between tumor metabolism and immunoediting, suggesting that PGK1 could serve as a potential immune-combination therapy target." (PMID 36358653, 2022). "However, in lung adenocarcinoma (LUAD), the role of PGK1 in altering the tumor microenvironment (TME) has not yet been determined." (PMID 36358653, 2022).
metastatic tumors (4 papers, 2020 to 2025). "The second Pgk1-dependent mechanism employed by metastatic tumors is to upregulate and redirect glycolysis to promote lactate synthesis despite abundant oxygen." (PMID 32338604, 2020). "Treatment of wild-type embryos with specific inhibitors of glycolysis or lactate synthesis or secretion mimicked the effects of pgk1-/-, indicating that the affected cell types require ‘aerobic glycolysis’, similar to the Warburg Effect exhibited by metastatic tumors." (PMID 32338604, 2020). "Furthermore, metastatic tumors exhibited higher levels of PGK1 mRNA compared to primary tumors." (PMID 38163864, 2024). "At the same time, the expression of PGK1 in brain metastatic and lymph node metastatic tumor cells is higher than that in primary tumor and normal epithelium cells, which may be the reason for the increased expression of PGK1 with the increase in the tumor grade and stage." (PMID 36358653, 2022). "In metastatic tumors, pathway and TF analyses revealed strong hypoxia-inducible factor-1α–driven hypoxia activation, influencing glycolysis (SLC2A1, SLC2A3, PGK1, PDK1, PGM1, and ALDOA), angiogenesis (ANGPTL4 and ADM), and survival in low oxygen (BNIP3, BNIP3L, and NDRG1)." (PMID 40736012, 2025). "We considered two distinct mechanisms for non-autonomous functions of Pgk1 that have been documented in metastatic tumors." (PMID 32338604, 2020).
spinal muscular atrophy (4 papers, 2022 to 2024). A motor neuron disease that affect the muscles, and characterized by muscle weakness and atrophy resulting from progressive degeneration and irreversible loss of the anterior horn cells in the spinal cord (i.e., lower motor neurons) and the brain stem nuclei. "PGK1 deficiency is associated with anemia syndromes that include the progressive onset of weakness, fatigue, and lassitude and motor neuron vulnerability in spinal muscular atrophy (SMA)." (PMID 35563647, 2022). "It is notable that in a mouse model of spinal muscular atrophy, Boyd and colleagues found a strong correlation between PGK1 expression and the resilience to spinal cord motor neuron degeneration and that overexpression of PGK1 was strongly protective in a zebrafish model of this genetic disease." (PMID 39167658, 2024). "Phosphoglycerate kinase 1 (PGK1) is a vital glycolytic enzyme that produces adenosine triphosphate through catalyzing the conversion of 1,3-diphosphoglycerate to 3-phosphoglycerate, which has been implicated in spinal muscular atrophy and collagen-induced arthritis (CIA)." (PMID 36964567, 2023).
Stroke (4 papers, 2017 to 2025). Sudden impairment of blood flow to a part of the brain due to occlusion or rupture of an artery to the brain. "Nevertheless, the study demonstrated new roles of PGK1 and glycolysis in stroke." (PMID 36749430, 2023). "However, the exact role of PGK1/glycolysis in stroke remains to be elucidated." (PMID 36749430, 2023). "However, the roles of PGK1 in glycolysis and stroke remain to be elucidated." (PMID 36749430, 2023). "PGK1 could promote ischemia/reperfusion injury-induced microglial M1 polarization and inflammation by regulating glycolysis, which might provide a novel direction in developing new therapeutic medications for preventing or treating stroke." (PMID 36749430, 2023). "In conclusion, PGK1 upregulation by the p300/H3K27ac pathway promoted oxygen glucose deprivation-induced microglial cell M1 polarization and inflammation by regulating glycolysis, providing a novel direction in developing new therapeutic medications for the prevention or stroke." (PMID 36749430, 2023). "Therefore, if an ideal PGK1 activator can be identified and screened for apoptosis inhibitors, it will certainly be possible to develop neuroprotective drugs for the treatment of stroke." (PMID 35387336, 2022). "Phosphoglycerate kinase 1 (PGK1) facilitates energy production with biosynthesis in many diseases, including stroke." (PMID 36749430, 2023). "Terazosin activates HSP90 via phosphoglycerate kinase-1 (PGK1), thereby enhancing tolerance to cellular stress, inhibiting apoptosis, and protecting stressed cells while alleviating stroke symptoms in rats." (PMID 35387336, 2022).
thyroid cancer (4 papers, 2021 to 2025). "This study aimed to investigate the association between PGK1 expression in thyroid cancer tissues and clinicopathological features, postoperative recurrence, and prognosis to provide clinical assessment and intervention reference." (PMID 40771921, 2025). "In addition, inhibition of the overexpressed phosphoglycerate kinase 1 (PGK1) via lncRNA papillary thyroid cancer susceptibility candidate 3 (PTCSC3) suppresses TC progression significantly." (PMID 40069775, 2025). "Initially, we analyzed the relationship between PGK1 expression levels and the 10-year survival rate of patients with thyroid carcinoma (THCA) in UALCAN database." (PMID 40771921, 2025). "Besides, we also analysed the correlation of PGK1 expression with the 10-year survival rate of patients with thyroid carcinoma (THCA) in UALCAN database." (PMID 40771921, 2025). "However, the precise mechanisms of PGK1 regulating glycolysis and tumorigenesis in thyroid cancer are largely unknown." (PMID 34337858, 2021). "Furthermore, when treating PTCSC3 overexpressed TPC‐1 and BCPAP cells with the proteasome inhibitor MG132, the protein levels of endogenous PGK1 increased more than those in control cells, suggesting that PTCSC3 promotes the proteasome‐dependent degradation of PGK1 in thyroid cancer cells." (PMID 34337858, 2021).
anemia (3 papers, 2019 to 2024). A reduction in the number of red blood cells, the amount of hemoglobin, and/or the volume of packed red blood cells. "In humans, PGK1 mutations present usually in three broad clinical deficits characterized by symptoms associated with anemia, myopathy, and neurological dysfunction." (PMID 39167658, 2024). "Despite PGK1 being a ubiquitous enzyme, the clinical presentation of PGK1 deficiency depends on three tissues: Erythrocytes (anemia), skeletal muscle (myopathy), and the central nervous system (CNS)." (PMID 31658606, 2019). "In some cases, PGK1-deficient patients exhibit only muscular symptoms without anemia." (PMID 31658606, 2019). "However, although the mechanism underlying this clinical heterogeneity of PGK1 deficiency remains unknown, we can conclude with dichotomization in myopathic forms without anemia and hemolytic forms." (PMID 31658606, 2019). "In addition, the potentially related diseases to specific patients’ proteins were anemias or hematopoietic system diseases (proteins HBZ, EPB41, HP, PGK1, HBE1, BPGM, and ALDOA)." (PMID 36519745, 2022).
gastric tumors (3 papers, 2018 to 2024). "The phosphoglycerate kinase 1 (PGK1) gene expression was shown to be significantly increased among patients with peritoneal dissemination of gastric tumors." (PMID 38596287, 2024).
head and neck squamous cell carcinoma (3 papers, 2021 to 2025). A squamous cell carcinoma that arises from any of the following anatomic sites: lip and oral cavity, nasal cavity, paranasal sinuses, pharynx, larynx, and salivary glands. "Meanwhile, in head and neck squamous cell carcinoma (HNSCC), the expression levels of PGK1 and SLC2A1 were upregulated and were significantly associated with the patients’ poorer overall survival (OS), disease-free survival (DFS) and relapse-free survival (RFS)." (PMID 40821990, 2025).
heart failure (3 papers, 2010 to 2022). Inability of the heart to pump blood at an adequate rate to meet tissue metabolic requirements. "The most stable reference genes were Rpl32, Gapdh and Polr2a in mouse post-infarction heart failure, Polr2a, Rpl32 and Tbp in rat post-infarction heart failure and Rpl32 and Pgk1 in human heart failure (ischemic disease and cardiomyopathy)." (PMID 20331858, 2010). "PGK1 has been also reported as appropriate internal control in two analyses of human heart failure, suggesting all of these genes might serve as reliable RGs." (PMID 35439923, 2022). "NAD+ was essential for ATP production around lysosomes and the GAPDH/PGK1 complex was associated with lysosomes, suggesting that reduced NAD+ due to mitochondrial translation deficiency is an important cause of heart failure." (PMID 33528041, 2021). "In the set of tested reference genes, the most stable reference genes were Rpl32, Gapdh and Polr2a in mouse post-infarction heart failure, Polr2a, Rpl32 and Tbp in rat post-infarction heart failure and Rpl32 and Pgk1 in human heart failure (ischemic disease and cardiomyopathy)." (PMID 20331858, 2010).
infiltrating ductal carcinoma (3 papers, 2017 to 2021). "Our present results showed that in a statistical average of 100 cases of invasive ductal carcinoma an increase of some key glycolytic enzymes occurred, namely: ALDOA, G3P KPYM, PGK1, and LDHA, while no relevant increase was observed for other glycolytic enzymes (i.e., ENOA, PGAM1, TPIS)." (PMID 28686225, 2017).
Intellectual disability (3 papers, 2019 to 2023). "Variable symptoms have been observed in patients with PGK1 deficiency, including chronic anemia, exercise intolerant myopathy, muscle weakness, cramping, myalgia, myoglobinuria, and intellectual disability." (PMID 34445777, 2021). "PGK1 deficiency has been reported to be associated with chronic anemia, exercise-intolerant myopathy, muscle weakness, cramping, myalgia, myoglobinuria, and intellectual disability." (PMID 37511607, 2023).
myocarditis (3 papers, 2024 to 2026). Myocarditis is a condition that is characterized by inflammation of the heart muscle (myocardium). "Inhibition of PGK1 by NG52 reduced the cardiac damage caused by myocarditis and altered the infiltration patterns of CD4+ T cells, including Th17 cells, Th1 cells, and Tregs." (PMID 40356915, 2025). "Lu’s research found that in myocarditis, both glycolysis and PGK1 expression are elevated in cardiac CD4+ T cells and Th17 cells." (PMID 40356915, 2025). "This study suggests that targeting PGK1 may be a promising approach for the treatment of ICI-induced myocarditis." (PMID 40356915, 2025). "By integrating nanotechnology with PGK1 inhibition, this approach preserves the anti-tumor efficacy of ICIs while minimizing irAEs, providing a refined and transformative strategy for treating ICI-induced myocarditis." (PMID 40356915, 2025).
thyroid papillary carcinoma (3 papers, 2019 to 2025). "Experimental data suggest that PTCSC3 has antitumor properties, as its overexpression inhibits thyroid papillary carcinoma cell proliferation and development in vitro and in vivo by suppressing glycolysis and promoting PGK1 ubiquitin-mediated degradation." (PMID 37968670, 2023). "The expression characteristics of 12 candidate reference genes (GAPDH, ACTB, HPRT1, TBP, B2M, PPIA, 18SrRNA, HMBS, GUSB, PGK1, RPLP0, and PGM1) were assessed by qRT-PCR in 45 thyroid tissue samples (15 papillary thyroid carcinoma, 15 paired normal tissues and 15 multinodular goiters)." (PMID 31645594, 2019).
tongue squamous cell carcinoma (3 papers, 2022 to 2024). A squamous cell carcinoma that arises from the tongue. "In tongue squamous cell carcinoma (TSCC) cells, SNHG26 directly binds to the PGK1 protein, inhibiting its ubiquitination and activating the Akt/mTOR signalling pathway." (PMID 37723547, 2023).
type 2 diabetes mellitus (3 papers, 2018 to 2022). A type of diabetes mellitus that is characterized by insulin resistance or desensitization and increased blood glucose levels. "For the first time, we report the association of HIF-1 activation with the antimicrobial peptide LL-37 and HIF-1 target genes PGK1 and IL-1B in type 2 diabetic patients living at high altitude." (PMID 34651203, 2022). "Glycolysis (triosephosphate isomerase 1 and phosphoglycerate kinase 1), citrate cycle (citrate synthase and malate dehydrogenase 2) and type II diabetes mellitus (pyruvate kinase) were among the other pathways identified for these proteins." (PMID 30419808, 2018). "Interestingly, we observed significantly increased expression of HIF1A and HIF-1 target gene PGK1 in exfoliated urine cells from type 2 diabetic patients living at high altitude." (PMID 34651203, 2022).
virus infection (3 papers, 2023 to 2025). "The results showed that viral infection led to an increased accumulation of PGK1 protein in the mitochondria." (PMID 40055833, 2025). "This indicates that the effect of PGK1 signalling on β-catenin expression is reversed during virus infection." (PMID 40055833, 2025). "This indicates no contamination between the fractions and supports our conclusion that viral infection results in the depletion of PGK1 protein in both fractions." (PMID 40055833, 2025). "Overexpression of β-catenin reduces PGK1 steady-state protein levels while overexpressing PGK1 boosts β-catenin protein expression—a phenomenon that reverses upon virus infection." (PMID 40055833, 2025). "Surprisingly, when we knocked down PGK1 levels protein before virus infection, we observed a significant increase in β-catenin expression in virus-infected cells." (PMID 40055833, 2025). "To further investigate how PGK1 proteins were re-localised following virus infection, we purified fractions from the cytosol and nucleus of MDBK cells that were either mock-infected or virus-infected." (PMID 40055833, 2025). "In this study, we discovered that PGK1 signalling significantly influences BoHV-1 replication, with the virus infection leading to a marked increase in the accumulation of PGK1 proteins in mitochondria." (PMID 40055833, 2025). "Specifically, after viral infection, the levels of mitochondrial PGK1 protein rose nearly 1.92-fold compared to mock-infected cells." (PMID 40055833, 2025). "We aimed to determine whether virus infection affects the subcellular localisation of PGK1, particularly within mitochondria." (PMID 40055833, 2025). "Interestingly, PGK1 signalling stimulates β-catenin-dependent transcriptional activity both in the absence and presence of viral infection, as verified by luciferase assay." (PMID 40055833, 2025). "Significantly, viral infection reduced the steady-state expression of PGK1 protein." (PMID 40055833, 2025). "In addition, virus infection differentially altered mRNA levels of PGK1, SMIT, and BGT-1, the canonical downstream targets regulated by NFAT5." (PMID 37227295, 2023). "To investigate whether the accumulation of proteins in mitochondria is affected by viral infection at 24 h after infection, we purified mitochondrial proteins using a commercial kit (Beyotime Biotechnology, cat# C3601), and PGK1 was immunoprobed via western blotting." (PMID 40055833, 2025). "Therefore, both PGK1 protein and mRNA levels were diminished in response to virus infection." (PMID 40055833, 2025). "The mRNA levels of the canonical downstream targets regulated by NFAT5 signaling, including PGK1, SMIT, and BGT-1, were differentially altered by virus infection with unexpected manners." (PMID 37227295, 2023). "Our data indicated that the virus infection altered the transcription of these molecules in diverse manners: PGK1 and SMIT were decreased to 70% and 18%, respectively, BGT-1mRNA levels were increased to approximately 5.54-fold, following virus infection." (PMID 37227295, 2023).
X-linked disease (3 papers, 2012 to 2020). X-linked form of disease. "PGK1 deficiency is an X-linked inherited disease (OMIM# 300653); the human PGK1 gene contains 11 exons and spans approximately 23 kilobases in Xq21.1." (PMID 31658606, 2019). "PGK1 deficiency is an uncommon X-linked inherited disorder, generally characterized by various combinations of non-spherocytic hemolytic anemia, neurological dysfunctions, and myopathies." (PMID 22348148, 2012).
amyloid (2 papers, 2023). "GPI, PGK1 and TPI1 were elevated in AD compared to AsymAD (p < 0.05), suggesting their elevation is related to cognitive dysfunction as opposed to amyloid pathology." (PMID 37461556, 2023).
autoimmune myocarditis (2 papers, 2024 to 2025). Autoimmune myocarditis is an autoimmune disease that affects the heart. "It was previously shown that PGK1 inhibition with NG52 treatment attenuates autoimmune myocarditis in mice through suppressing CD4+ T cell activation and differentiation into Th17 cells." (PMID 40260243, 2025). "Furthermore, NG52 inhibited the activation and differentiation of CD4+ T cells, suggesting that PGK1 may play a key role in the metabolic regulation of T cell differentiation and autoimmune myocarditis." (PMID 39712033, 2024).
Cognitive impairment (2 papers, 2016 to 2022). Abnormal cognition is characterized by deficits in thinking, reasoning, or remembering. "PGK1 and miR3185 are both attractive biomarker targets that could potentially be used to detect the onset of mood- and fatigue-associated cognitive impairment in salivary exosomes." (PMID 35563647, 2022).